INS (insulin)
Diseases named in the same sentence as INS in open-access papers (continued):
Sharing a sentence is not in itself a finding about the gene and the disease.
Insulin resistance (continued). "Therefore, while excess fatty acids and glucose stimulate insulin release to convert glucose into glycogen and fat, the presence of ectopic fat in obese individuals contributes to peripheral insulin resistance." (PMID 40622971, 2025). "Insulin-treated patients generally exhibit greater insulin resistance, necessitating exogenous insulin administration, which may further drive metabolic adaptations." (PMID 40136665, 2025). "Triglyceride-glucose (TyG) and triglyceride glucose-body mass index (TyG-BMI), due to their ease of measurement and non-invasive nature, are replacing the high insulin normal glucose clamp test and Homeostasis Model Assessment of Insulin Resistance (HOMA-IR) as simple indicators for IR testing." (PMID 39931234, 2025). "Increased insulin resistance is thought to play a role in this connection, and previous studies indicated that improved insulin sensitivity following either treatment with metformin or weight loss could delay pubertal progression in girls with overweight." (PMID 41291865, 2025). "Furthermore, AD also affects insulin signaling in the brain, with some researchers referring to it as "type III diabetes" due to its association with insulin resistance." (PMID 41326893, 2025). "Interestingly, SD-OP animals exhibited hyperinsulinemia and insulin resistance, with higher fasting serum insulin and HOMA-IR levels compared to both SD-OR and HFD-OP groups." (PMID 40622971, 2025). "Insulin-stimulated activation of phosphatidylinositol 3-kinase (PI3K) is also reduced in insulin resistance and may act through Akt-independent targets." (PMID 40631311, 2025). "Clinical diagnostic criteria for T2D includes insulin resistance, non-autoimmune decreased insulin production from β-cells of the pancreas, and hyperglycemia." (PMID 40337247, 2025). "Additionally, fasting insulin and insulin resistance index were also higher in the development group, with statistical significance observed." (PMID 40150457, 2025). "However, insulin resistance is frequently accompanied by dyslipidemia, and HDL-c, a key anti-atherosclerotic lipoprotein, is intimately linked to insulin sensitivity." (PMID 40626240, 2025). "Moreover, the AIP can induce chronic inflammation, with inflammatory cytokines interfering with insulin signaling pathways, leading to insulin resistance." (PMID 40130162, 2025). "Insulin resistance creates an increased demand for insulin secretion from beta cells." (PMID 39940428, 2025). "Meanwhile, Obesity also disrupts cellular response to insulin, contributing to insulin resistance." (PMID 40671123, 2025). "Furthermore, in mice with high-fat diet-induced insulin resistance, a two-week adiponectin treatment significantly improved insulin sensitivity and reduced ectopic lipid accumulation in both the liver and skeletal muscle." (PMID 41226331, 2025). "Thus, the proinflammatory state was shown to contribute to T2DM by increasing peripheral insulin resistance and impairing insulin secretion." (PMID 41226484, 2025). "Insulin resistance, often driven by obesity and sedentary lifestyles, is exacerbated during specific phases of the menstrual cycle, such as the luteal phase, when progesterone levels are elevated, potentially impairing insulin sensitivity." (PMID 40658669, 2025). "In addition to the genes involved in insulin signaling for instance glucose transporters, other loci involved in insulin resistance and T2D include the genes BCL2, FAM19A2, CCND2, PAM, PDX1, and Cyp450." (PMID 39859066, 2025). "This dilation may affect the distribution and utilization of glucose in tissues, impairing insulin signaling pathways and exacerbating insulin resistance." (PMID 41036090, 2025). "According to this, the insulin resistance was measured in three main ways: impaired fasting glucose; impaired glucose tolerance; or via an elevated homeostatic model assessment of insulin resistance, which takes into account the proportionality between fasting insulin and fasting glucose." (PMID 40514488, 2025).
Insulin resistance (continued). "Furthermore, based on animal studies, IRI inhibits insulin secretion and induces insulin resistance by dysregulation of insulin signals." (PMID 40931439, 2025). "Analysis from six randomised controlled trials (331 participants) showed significant improvements with omega-3 supplementation in women with GDM compared to a placebo group: fasting glucose decreased by 0.25 mmol/L, fasting insulin by 17.13 pmol/L, and insulin resistance by 0.51." (PMID 40218968, 2025). "Furthermore, neutrophil‐derived factors, such as NE, can impair insulin signaling in hepatocytes and adipocytes, contributing to insulin resistance." (PMID 39845896, 2025). "Sirtuins can affect both insulin secretion and the development of insulin resistance." (PMID 40725501, 2025). "T2DM is characterised by a diminished insulin response, also known as insulin resistance." (PMID 41404215, 2025). "Impaired insulin signaling in adipocytes leads to increased production of pro-inflammatory cytokines and recruitment of immune cells, establishing a feed-forward loop between insulin resistance and inflammation." (PMID 41472730, 2025). "The activation of these pathways in the context of GDF15 deficiency and high lipid content may have a strong impact on insulin signaling, thereby contributing to insulin resistance." (PMID 39825925, 2025). "Thirdly, lipoprotein remnants in RC can interfere with intracellular insulin signaling pathways, potentially binding to insulin receptors or disrupting the phosphorylation and activation of insulin receptor substrates, thereby exacerbating insulin resistance." (PMID 39508748, 2025). "Glymphatic function was assessed using the diffusion tensor imaging along the perivascular space (DTI‐ALPS) index, insulin sensitivity was assessed by the homeostasis model assessment–estimated insulin resistance index (HOMA‐IR), and HOMA‐IR≥2.80 was defined as insulin resistance (IR)." (PMID 41431341, 2025). "Changes in glycemic outcomes (HbA1c, FBG, and fasting insulin), insulin resistance/sensitivity markers (HOMA-IR, HOMA-B, and QUICKI), diastolic blood pressure, and lipid parameters (total cholesterol, triglycerides, LDL-C, non-HDL-C, and HDL-C) were similar between the sexes (p > 0.05)." (PMID 40843316, 2025). "Given the role of insulin resistance in PD pathogenesis and the ability of exercise to mitigate it, insulin may serve as a valuable biomarker for assessing exercise responsiveness in individuals with PD." (PMID 40595707, 2025). "Insulin resistance disrupts insulin PI-3 kinase and Akt-dependent signaling pathways." (PMID 40076851, 2025). "Insulin resistance (IR) is a metabolic disorder characterized by an impaired response to insulin." (PMID 40278374, 2025). "Interestingly, although knocking down Mfn1 in the liver confers protection to mice against high-fat diet-stimulated insulin resistance and obesity, inhibiting the division-related proteins Fis1 and Drp1 in cells impairs cell respiration and insulin secretion." (PMID 40851002, 2025). "Nevertheless, long-term high insulin exposure may aggravate insulin resistance and lead to islet B cell failure in T2DM." (PMID 40641746, 2025). "Furthermore, Sotagliflozin improves insulin sensitivity, reduces insulin resistance, and stimulates fat metabolism." (PMID 40529829, 2025). "Insulin resistance is defined as “reduced sensitivity in body tissues to the action of insulin”." (PMID 39859258, 2025). "In adipose tissue, PYY may facilitate lipid mobilization and indirectly improve insulin sensitivity by mitigating inflammation and reducing adipocyte hypertrophy—both of which are characteristic features of insulin resistance." (PMID 41228539, 2025). "In addition to its effects on liver fat, PF-06835919 has shown improvements in glucose levels, insulin sensitivity, and the homeostatic model assessment of insulin resistance." (PMID 40243565, 2025).
Insulin resistance (continued). "Our results demonstrate that HFD-induced obesity and insulin resistance significantly alter exosomal content, leading to profound molecular and phenotypic changes upon uptake into breast cancer cells, compared to lean and insulin sensitive controls." (PMID 40629272, 2025). "POPs have direct effects on insulin signaling leading to insulin resistance." (PMID 39775248, 2025). "T2DM is characterized by insulin insensitivity due to insulin resistance." (PMID 39136514, 2025). "The impact of these pharmacological modalities on glucose metabolism may be attributed to their capacity to induce insulin resistance, inhibit insulin secretion, and exert direct cytotoxic effects on pancreatic cells." (PMID 41155560, 2025). "The influx of FFAs contributes to insulin resistance, enhanced hepatic glucose production, impaired insulin degradation, and subsequent hyperinsulinemia, which collectively promote triglyceride synthesis, hepatic steatosis, and the development of non‐alcoholic fatty liver disease (NAFLD)." (PMID 41284359, 2025). "Interestingly, upregulation of muscle BDNF was associated with decreased insulin resistance (i.e., HOMA2-IR), suggesting a potential insulin-sensitizing effect of BDNF." (PMID 40171198, 2025). "T2DM is a non-insulin-dependent type of DM and is associated with insulin resistance, decreased insulin sensitivity, and lipid metabolism disorder, which lead to hyperglycemia, oxidative stress, and inflammation." (PMID 39136514, 2025). "Consequently, chitosan can enhance insulin secretion, improve gut microbiota, and reduce insulin resistance." (PMID 40703749, 2025). "As another potential pathway, the elevated expression of a kinase, Src-Homology Inositol Phosphatase-2 (SHIP2) that hydrolyzes PIP3 to PIP2, could reduce insulin signaling and contribute to insulin resistance in T2D." (PMID 41393296, 2025). "These hormones can interfere with insulin sensitivity, leading to insulin resistance and GDM." (PMID 39997932, 2025). "In BRCA gene mutation carriers, defective ER signaling promotes insulin resistance; however, compensatory high levels of insulin and IGF-1 do not successfully improve glucose uptake." (PMID 41514592, 2025). "Hyperinsulinemia refers to excess insulin levels in the blood due to insulin resistance." (PMID 41169480, 2025). "Improved glucose, HbA1c, insulin, insulin resistance, CRP, antioxidant capacity, PON-1." (PMID 40733199, 2025). "The HFD induces brain insulin resistance by reducing the tyrosine phosphorylation of the insulin receptor and increasing the serine phosphorylation of insulin receptor substrate 1, which can disrupt the proteins involved in the insulin signaling pathway." (PMID 40149843, 2025). "In particular, visceral adiposity, in which fat accumulates around the internal organs, tends to cause insulin resistance, a condition in which insulin does not function sufficiently." (PMID 40220069, 2025). "Both groups exhibited improvement in HOMA-IR (reflecting whole-body insulin resistance) and the disposition index (reflecting insulin secretion relative to action), and while the insulin sensitivity index rose in both groups, it tended to rise more in the LowLF group." (PMID 40309768, 2025). "Additionally, multiple studies have reported that changes in extracellular pH are often accompanied by intracellular pH alterations, which can influence insulin secretion and contribute to insulin resistance." (PMID 40427349, 2025). "Impairment of insulin signaling in the CNS, as a consequence of central insulin resistance, may lead to hyperphagia, weight gain, obesity, and the potentiation of gluconeogenesis by the liver." (PMID 41009753, 2025). "Its sensitivity and specificity in distinguishing women who will require insulin therapy may be significantly improved through its integration with other surrogate markers of insulin resistance." (PMID 41225974, 2025). "First, insulin resistance is often accompanied by high insulin levels." (PMID 41064293, 2025).
Insulin resistance (continued). "While the exact molecular link between glutamate excitotoxicity and brain insulin resistance remains unclear, glutamate has been demonstrated to reduce tyrosine phosphorylation of the insulin receptor in insulin-stimulated hippocampal neuronal cultures." (PMID 41294899, 2025). "The pathogenesis of insulin resistance (IR) involves a complex interplay of β-cell dysfunction, lipid overload, chronic inflammation, and oxidative stress, all of which converge to disrupt insulin signaling." (PMID 40881124, 2025). "T2DM is characterized by insulin resistance and relatively insufficient insulin secretion." (PMID 40650120, 2025). "Most were of patients treated with oral hypoglycemic agents (61.3%), while 17.3% received combination therapy with insulin, a pattern that may reflect more advanced disease or increased insulin resistance." (PMID 40786180, 2025). "Glycemic indices, such as fasting glucose and insulin, oral glucose tolerance, insulin tolerance, and homeostasis model of insulin resistance (HOMA-IR) scores, as well as the activity level of liver antioxidant and pro-oxidant enzymes, were evaluated in STZ-induced GDM rats." (PMID 41488874, 2025). "EBN supplementation has also been shown to improve glucose tolerance and reduce fasting blood glucose (FBG), serum insulin levels, and the homeostatic model assessment of insulin resistance (HOMA-IR) values by upregulating key components of the insulin signaling cascade." (PMID 40429763, 2025). "Some evidence supports that supplementation with MI and DCI improves insulin sensitivity, particularly in men, suggesting that dietary inositol could be a promising adjuvant therapy in men with insulin resistance." (PMID 41228532, 2025). "In addition, obesity is associated with increased circulating levels of LPS, which triggers insulin resistance by inducing inflammatory signals that interfere with insulin signaling." (PMID 39269560, 2025). "miR-21 shows context-dependent effects: by suppressing PTEN it elevates AKT and can acutely enhance NRF2/ARE responses, whereas chronic AKT→mTOR/S6K signaling may impair proximal insulin signaling and favor insulin resistance." (PMID 41480360, 2025). "Despite the lack of direct binding, STAT3 is still retained as a core target because it plays a core role in the PPI network (degree = 49, ranking first in connectivity) and participates in the insulin resistance process through signaling pathways such as insulin resistance and HIF-1." (PMID 40508108, 2025). "This investigation demonstrated no opposing effects of CLA on insulin signaling, despite its common association with insulin resistance (Pinto Júnior and Seraphim 2012)." (PMID 40697709, 2025). "It upregulates glucagon‐like peptide‐1 receptor (GLP‐1R) expression in the pancreas, inhibits caspase family proteins and AIF, promoting β‐cell proliferation, preventing β‐cell apoptosis, increasing serum insulin levels, alleviating insulin resistance, and reducing fasting blood glucose." (PMID 40336535, 2025). "In the same article, the authors showed that the non-diabetic T allele carriers had lower HOMA-IR and fasting insulin values and an absence of insulin resistance." (PMID 40428311, 2025). "Furthermore, elevated ceramide levels are known to interfere with insulin’s ability to activate protein kinase B, further promoting insulin resistance." (PMID 40700071, 2025). "In addition, fructose diets impair insulin sensitivity by lipogenesis, resulting in insulin resistance and, eventually, type 2 diabetes." (PMID 40141836, 2025). "Insulin resistance will lead to reduced insulin sensitivity and altered metabolic states, whereas absolute absence of insulin will cause a catabolic state and promote ketogenesis." (PMID 40480914, 2025). "Smoking could reduce insulin sensitivity, enhance insulin resistance, and thereby lead to obesity and overweight, increasing the risk of MS." (PMID 41450839, 2025).
Insulin resistance (continued). "Insulin resistance is when a cell or tissue cannot correctly respond to regular amounts of insulin." (PMID 40362446, 2025). "Several reports documented that, independent of insulin signaling, glucose activates mTOR, which in turn, has a negative feedback loop, blocking the insulin-dependent signaling pathway causing insulin resistance." (PMID 40277891, 2025). "Our patient had a significant decrease in insulin levels after 12 weeks of treatment, which likely lowered his insulin resistance and may have contributed to his reduced alcohol cravings." (PMID 40375882, 2025). "This could be because the accumulation of intrahepatic fat is associated with that of intrahepatic ceramides and diacylglycerols, which inhibit insulin signaling and, therefore, promote hepatic insulin resistance." (PMID 40469667, 2025). "Research indicates that PFAS may disrupt insulin signaling pathways, contributing to insulin resistance, a key factor in the development of type 2 diabetes." (PMID 40137495, 2025). "In addition, CIT was reduced in men with insulin resistance and T2D compared to insulin-sensitive individuals." (PMID 40872649, 2025). "Elderly people tend to accumulate fat in ectopic tissues, mainly liver and skeletal muscle, a factor that may elicit insulin resistance or impaired insulin secretion and ultimately T2DM." (PMID 40559420, 2025). "Chronic PM2.5 exposure activated Nrf2-mediated oxidative stress response and enhanced JNK-dependent inhibitory signaling cascades, ultimately resulting in hepatic insulin resistance, which highlights the link between hepatic oxidative stress and insulin resistance." (PMID 39859525, 2025). "Moreover, insulin resistance disrupts lipid metabolism, resulting in intramyocellular lipid accumulation, which further impairs insulin signaling and downstream metabolism." (PMID 40290665, 2025). "Indeed, reductions in insulin-stimulated pAkt and GLUT4 levels as well as consistently reduced insulin-stimulated glucose uptake provide convincing evidence of the reliability in palmitate-treated myotubes as a model of skeletal muscle insulin resistance." (PMID 41305671, 2025). "Furthermore, it shows elevated insulin signaling, adipogenesis and adipocytokine signaling pathways, all pointing towards insulin resistance and related to the known ATAD3A effect on fatty-acid metabolism." (PMID 40234890, 2025). "Visceral fat may secrete inflammatory cytokines and adipokines, which can interfere with insulin signaling and contribute to insulin resistance." (PMID 40261649, 2025). "Conversely, abnormal alanine metabolism may also feedback and affect the action of insulin, aggravating insulin resistance." (PMID 40248150, 2025). "IRS4 is part of insulin signaling pathway and its upregulation can lead to insulin resistance." (PMID 40473938, 2025). "Since these hormones play a key role in mediating insulin resistance during pregnancy, an unexpected decline in insulin requirements during the third trimester may be indicative of reduced placental function." (PMID 41227133, 2025). "GLP-1R may ameliorate these conditions by improving insulin signaling and reducing insulin resistance in the brain." (PMID 40778306, 2025). "Thus, these sites represent emergent or new insulin-regulated phosphorylations in the context of insulin resistance." (PMID 40231468, 2025). "In all participants, anthropometric measurements and the following laboratory tests were performed: fasting plasma glucose, glycated hemoglobin (HbA1c) and serum iron, lipid profile, insulin, Homeostatic Model Assessment for Insulin Resistance (HOMA-IR), C-reactive protein (CRP), ERFE and hepcidin." (PMID 41156458, 2025). "Moreover, by binding to its receptors, adiponectin enhances insulin sensitivity, and is downregulated in individuals with obesity and insulin resistance." (PMID 40453737, 2025). "In cases of severe insulin resistance, high-dose insulin may be necessary to optimize glycemic control." (PMID 40452043, 2025).